ZNF429 (zinc finger protein 429)
Description:
May be involved in transcriptional regulation.
Tractability: PROTAC: ubiquitination databases record sites on it.
Gene: Protein-coding gene on chromosome 19 (21,496,682 to 21,556,270, forward strand). Ensembl gene ENSG00000197013.
Subcellular location: Nucleus
Subcellular location (Human Protein Atlas): Nucleoplasm
Pathways (Reactome):
Gene expression (Transcription): Generic Transcription Pathway
Gene Ontology:
Molecular function: DNA-binding transcription factor activity, RNA polymerase II-specific; RNA polymerase II cis-regulatory region sequence-specific DNA binding
Biological process: regulation of transcription by RNA polymerase II; negative regulation of transcription by RNA polymerase II; regulation of DNA-templated transcription
Cellular component: nucleus
Genetic constraint (gnomAD): Loss-of-function variants: 46 observed, 51.24 expected, observed/expected ratio (o/e) 0.9, 90% interval 0.71 to 1.15. The upper end of that interval is the gene's LOEUF score, 1.15, which puts it in group 5 of 6, group 1 being the genes least tolerant of losing a copy. Missense variants: 811 observed, 770.21 expected, observed/expected ratio (o/e) 1.05, 90% interval 0.99 to 1.12. Synonymous variants: 270 observed, 257.29 expected, observed/expected ratio (o/e) 1.05, 90% interval 0.95 to 1.16.
Homologues: Orthologues: chimpanzee ZNF429 (99% identical), macaque ZNF429 (95% identical), mouse Zfp273 (45% identical), rat Zfp273l-ps1 (45% identical), mouse Zfp708 (43% identical), mouse Zfp85 (42% identical), rat LOC102547287 (42% identical), mouse Zfp87 (41% identical), rat Zfp708 (40% identical), mouse Zfp58 (40% identical), rat Rsl1 (37% identical), rat Zfp455l1 (36% identical), and 10 more. Paralogues in human: ZNF681 (66% identical), ZNF724 (64% identical), ZNF726 (63% identical), ZNF254 (63% identical), ZNF43 (62% identical), ZNF728 (60% identical), ZNF85 (59% identical), ZNF708 (58% identical), ZNF93 (58% identical), ZNF493 (57% identical), ZNF676 (53% identical), ZNF595 (52% identical), and 164 more.
Diseases named in the same sentence as ZNF429 in open-access papers:
ZNF429 is named in the same sentence as 16 diseases in open-access papers, as found by Europe PMC text mining. Sharing a sentence is not in itself a finding about the gene and the disease. The quoted sentences say what the papers report.
astrocytoma (1 paper, 2021).
Obesity (1 paper, 2020). Accumulation of substantial excess body fat. "Although there are no data to confirm that MAP7 and ZNF429 are relationship to obesity or T2DM, we believe that they may be closely related to the pathogenesis of O‐T2DM due to their mutations in the exon region and their significant changes in transcriptome expression levels." (PMID 31957265, 2020).
thymic carcinoma (1 paper, 2023). Thymic carcinoma (TC) is a type of thymic epithelial neoplasm characterized by a high malignant potential.
ZNF429 also shares sentences with these, for which no sentence is quoted: cancer (4 papers); bladder cancer (1); cervical cancer (1); colorectal adenocarcinoma (1); cutaneous melanoma (1); endometrioid carcinoma (1); glioblastoma (1); hepatocellular carcinoma (1); leiomyosarcoma (1); lung carcinoma (1); prostate carcinoma (1); renal carcinoma (1); tumor (1).